CXCL9 (C-X-C motif chemokine ligand 9)
Diseases named in the same sentence as CXCL9 in open-access papers (continued):
Sharing a sentence is not in itself a finding about the gene and the disease.
tumor (continued). "In our laboratory, we demonstrated that tumor-derived sonic hedgehog (Shh) ligand promotes M2-polarization of TAMs to suppress CD8+ T cell infiltration through downregulation of CXCL9 and CXCL10 and limit effector T cell functions by upregulating programmed death ligand-1 (PD-L1) expression on TAMs." (PMID 34771482, 2021). "We speculated that immune cells, such as dendritic cells and macrophages accumulating in tumor tissues responding to tumor cells for secreting in situ CXCL9, were vital for recruiting CD8+ T cells homing to tumor tissues." (PMID 34680466, 2021). "Added to this, there is the further complexity of tumours using epigenetic silencing to switch off production of Th1-based chemokines such as CXCL9 and CXCL10, a novel immune escape mechanism employed by tumours to reduce infiltration by cytotoxic effector cells." (PMID 34885108, 2021). "One of the possible explanations for such discrepancy is that perhaps even though the direct effect of CXCL10 and CXCL9 on effector T cells, and possibly endothelial cells is similar, their direct effect on tumor cells may vary." (PMID 34944943, 2021). "However, several studies have demonstrated that the CXCR3 axis provokes tumour growth and metastasis, and more in-depth investigation is needed to elucidate the CXCL9-related mechanism." (PMID 34527583, 2021). "In addition, combination treatment with GSK126 (a methyltransferase inhibitor) and LB201 (a class 1/2 HDAC inhibitor) enhances expression of CXCL9 and 10 in brain tumor cell lines, resulting in increased T cell trafficking toward tumor cells." (PMID 32560120, 2020). "Several studies showed that CXCL9 and CXCL10, particularly CXCL10 produced by tumor or host cells can recruit CXCR3+ tumor-infiltrating CD4+ T cells, CD8+ T cells and NK cells that are associated with tumor suppression." (PMID 32547545, 2020). "Low CXCL9 or PD-L1 was associated with shorter RFS in patients with higher tumor cell proliferation or without instillation therapy." (PMID 33003392, 2020). "Tumor cells express PD-L1 and secrete CXCL9 upon IFNγ receptor binding to IFNγ." (PMID 32795913, 2020). "High CXCL9 also correlated with remarkable abundance of tumor-infiltrating NK cells." (PMID 32784743, 2020). "The weight of PAAD tumour was potently increased in mice treated with CXCL9." (PMID 31913856, 2020). "Expression of CXCL9 in the tumour tissues of PAAD patients correlated with its CXCR3 expression and treatment of CXCL9 could significantly induce the expression of CXCR3 in CD8+ cytotoxic cells." (PMID 31913856, 2020). "Loss of function of the PBAF complex increased chromatin reachability to transcription regulator elements of IFN-γ-inducible genes within tumor cells and subsequently increased production of CXCL9/CXCL10 chemokines, allowing more efficient recruitment of Teffs to tumor tissue." (PMID 32850400, 2020). "Treatment of CXCL9 could significantly suppress the expression of anti-tumour cytokine, suggesting the dysfunction of cytotoxic T cells after CXCL9 cells." (PMID 31913856, 2020). "In our data, Mø_c1 represented the most abundant macrophages (37.10%) with high expression of IL1B, as well as CXCL10 and CXCL9, which might be involved in anti-tumor responses." (PMID 33298893, 2020). "Collectively, our results suggest that increased NF-κB signaling in TAMs induces anti-tumor immunity, including polarization of macrophages away from the pro-tumor M2 phenotype and subsequent recruitment of cytotoxic T cells, with concomitant increases in levels of CXCL9." (PMID 33028251, 2020). "As CXCL9 and CXCL10 shares same receptor CXCR3 in T lymphocytes, we would like to understand whether the CXCL9 has similar or opposite function with CXCL10 in regulating tumour microenvironment." (PMID 31913856, 2020).
tumor (continued). "Our data demonstrate that the increase in T cell trafficking into poorly infiltrated tumors following TGFβ blockade may rely on tumor and/or tumor microenvironment expression of CXCR3 ligands: CXCL9, CXCL10, or CXCL11." (PMID 32273499, 2020). "Literature suggests that CXCL9 may be a target for cancer therapy as it is a tumor suppressor, and, coupled with other chemokines, can act as a potent differentiator to T helper cells in naïve T cells." (PMID 33105566, 2020). "As CXCL9 treatment showed significant suppression on CD8+ population in PAAD tumour, the findings of adoptive transfer suggested that suppression of cytotoxic T cells could be responsible for the tumour-promoting action of CXCL9 in PAAD." (PMID 31913856, 2020). "By measuring the increase of luciferin signals, it was found that treatment of CXCL9 could significant accelerate the growth of PAAD tumour." (PMID 31913856, 2020). "The evidence strongly suggests that EP4 antagonist therapy increases the infiltration of effector CD8+ T cells into the tumor through the active production of chemokines CXCL9 and 10 from the DCs in tumors corresponding to the restoration of NK cell functions by EP4 signal inhibition." (PMID 32210957, 2020). "Similarly, after 6 weeks of treatment, durvalumab significantly increased tumor gene expression of T cell chemotactic chemokine CXCL9, the checkpoint molecule LAG3, and IFN-γ, but the clinical effects of these immune variations was unclear." (PMID 32670271, 2020). "•Metastatic CSMD3 mutated HGSOC showed objective and sustained response to pembrolizumab.•The tumor was massively infiltrated by CD8+ T cells while PD-L1 TPS was at 10%.•CSMD3 mutated HGSOC showed up-regulation of CCL5 and CXCL9." (PMID 32613071, 2020). "The tumor site resident cDC1s secrete CXCL9/10 chemokine to induce these tumor-specific CTLs." (PMID 32070016, 2020). "This transformation to “hot tumor” might relate with the expression of IFN-stimulated genes (ISG) such as CXCL9 and CXCL10, which could recruit APC and T cell to tumor." (PMID 30935414, 2019). "Moreover, cDC1 can produce key chemokines such as CXCL9/10 that will actively recruit more T cells to the tumor site." (PMID 30949170, 2019). "However, in primary tumor spheres IL-17 stimulation resulted in reduced levels of CXCL9 and 10 mRNAs, thus confirming a direct inhibitory role of IL-17 on CXCL9/10 production." (PMID 31775909, 2019). "We then investigated whether the TAM-specific expression of CXCL9 was responsible for the regulation of the tumor infiltration of CD8+ T cells." (PMID 31186412, 2019). "Moreover, in human cancers, overexpression of CXCL9 and CXCL10 is associated with a higher number of tumor-infiltrating lymphocytes and improved survival, e.g., in breast, ovarian, colon, lung, and several other cancers." (PMID 31482487, 2019). "CXCL9 activated T cells and NK cells through chemotaxis, and it cured cancer as anti-tumor agent." (PMID 30973890, 2019). "CXCL9 predominantly mediates lymphocytic infiltration and suppresses tumor growth." (PMID 31248118, 2019). "By maintaining high CXCL9/CXCL10 levels within the tumour, these ligands could interact with their cognate receptor, CXCR3, which was observed to be expressed higher on pre-cDC1 in the blood than on other DCs subsets." (PMID 31091774, 2019). "Our findings further demonstrated that deletion of Camkk2 in BMDM also results in increased expression of genes encoding CXCL9 and CXCL10 chemokines that attract and activate CXCR3 expressing cells, including Th1, CD8+ T cells, and NK cells, which positively regulate anti-tumor immunity." (PMID 31164648, 2019). "Moreover, cDC1s are critical for the transport of intact tumor-Ag to lymph nodes (LNs) to elicit anti-tumor T cell activation and the secretion of CXCL9/10 by tumor-infiltrating cDC1s is crucial for the recruitment of CD8+ T cells into tumors." (PMID 30961656, 2019).
tumor (continued). "Moreover, tumor-resident cDC1s are the predominant sources of CXCL9 and CXCL10 and mediate recruitment effector T cells into the tumor." (PMID 31143179, 2019). "CXCL9/10/11 lack the ELR motif thus attenuating angiogenesis to negatively impact on tumor growth." (PMID 30320116, 2018). "Importantly, Sipa1−/− MSCs, but rarely Wt MSCs, in Bcr-Abl+ tumor tissue preferentially and strongly expressed chemokine genes such as Cxcl9 (Mig) targeting memory T cells with minimal proinflammatory chemokines targeting myeloid cells." (PMID 29500416, 2018). "Inhibition of galectin-3 in human tumor biopsies enhanced IFN-γ-induced CXCL-9 chemokine expression, suggesting that the blockade of galectin-3 in tumor cells may promote T cell tumor infiltration and activation." (PMID 29389859, 2018). "CXCL9 expression is significantly elevated in NPC tumor tissue." (PMID 30142953, 2018). "Compared to the macrophages in WT group samples, the macrophages isolated from PKN2-WT tumor showed significantly higher expression of Il1b, Tnf, Cxcl9, Il23, Ros1 and Il12b and significantly lower expression of Tgfb1, Vegfa, Egf, Retnla and Il10, illustrating predominant M1 phenotype." (PMID 29368606, 2018). "The tumor tissue of Sipa1−/− mice contained remarkably abundant Cxcl9 compared to those of Wt mice." (PMID 29500416, 2018). "Blockade of CXCR3 on tumor cells, thus preventing metastasis, combined with increased skin expression of CXCL9/10/11 might be appropriate in circumstances where CXCR3+ effector T cells can reduce tumor growth." (PMID 30320116, 2018). "CXCL9 is a T- and NK-cell chemoattractant that displays antitumor and pro-tumor activities." (PMID 29967609, 2018). "A recent analysis of 20 different cytokines and chemokines (some also included here) in culture supernatants harvested from HNSCC tumor tissue-derived cell suspensions, showed, in accordance with the present study, high tumor related levels of CXCL9, CXCL10, and CCL20 and decreased levels of CCL5." (PMID 29587383, 2018). "We wondered whether an increased CXCL9 gradient upon galectin antagonist treatment was able to attract more T cells into the tumor." (PMID 28986561, 2017). "After treatment, the tumor pieces were frozen and CXCL9 mRNA was measured by RT-PCR." (PMID 28986561, 2017). "CXCL9 mRNA was measured in each section along the whole tumor, as a read-out of IFNγ signal." (PMID 28986561, 2017). "Hence, galectin-3 retains IFNγ in the tumor microenvironment, thereby decreasing the extension of a CXCL9 gradient." (PMID 28986561, 2017). "In response, local endothelial cells, and potentially the tumor cell itself, could increase local production of CXCL9 and CXCL10." (PMID 28358049, 2017). "We examined whether galectin-3 was able to modulate IFNγ-induced CXCL9 expression in human tumor cells." (PMID 28986561, 2017). "Whilst many CXCL-9-poor tumours have a demonstrably poorer prognosis (presumably due to reduced adaptive anti-cancer immunity) others appear to derive growth and invasion signals from CXCL-9 (e.g. via over-expression of the CXCR3 receptor)." (PMID 29157300, 2017). "Nevertheless, a more detailed characterization and mechanism of the role of CXCL9 in tumor biology is desperately required, as it may improve cancer treatment and possibly lead to clinical applications in cancer prognosis, diagnosis, and therapy." (PMID 27726306, 2016). "The complex role of CXCL9 in tumor might be due to the following reasons: First, CXCL9 plays an important role in tumor immunity." (PMID 27726306, 2016). "Second, the contradictory role of CXCL9 might be associated with its receptor's splice variants CXCR3‐A and CXCR3‐B, as they always showed a counteracting role in tumor progression." (PMID 27726306, 2016). "Accumulating evidence indicates that manipulation of the tumor microenvironment, which involves CXCL9, could enhance the therapeutic efficacy of strategies via tumor‐specific T cells." (PMID 27726306, 2016).
tumor (continued). "Similar to tumor tissues, CXCL9 protein levels were substantially increased in sera of mice in the combination group, although no CXCL10 could be detected." (PMID 28123870, 2016). "Although CXCL9 is considered as an anti‐tumor factor according to some reports, it could also promote the tumor development as follows." (PMID 27726306, 2016). "So far, doubts about the role of CXCL9 still exist in tumors, even in the same type of tumor." (PMID 27726306, 2016). "The up-regulation of CXCL9 in the lung might be involved in the increase of CD8+ cells in BALF of tumor-bearing iNOS-mice treated with GalCer." (PMID 26496031, 2015). "Furthermore, overexpression of CXCL9 resulted in the inhibition of NSCLC tumor growth and metastasis via a decrease in tumor-associated angiogenesis." (PMID 24971349, 2014). "Likewise, in a murine cutaneous tumour model, the recruitment of CXCR3-bearing effector cells by CXCL9 correlated positively with tumour rejection." (PMID 24961933, 2014). "In addition, the coupling of CXCL9 with its receptor CXCR3, has anti-angiogenic properties through direct interaction with the endothelium, causing suppression of tumor growth due to the suppression of neovascularization." (PMID 24278236, 2013). "Interestingly, our novel findings concerning expression levels of CXCL9, IL8, MMP1, MMP3 and COL1A1 are the converse of previously reported results: CXCL9 protein can modulate host cell infiltration and tumor behavior." (PMID 23405235, 2013). "Additionally, more in-vivo experiments and clinical trials are warranted to evaluate the role of CXCL9 for detecting tumor recurrence or distant metastasis in the future." (PMID 24278236, 2013). "However, in NPC, the potential correlation between the level of CXCL9 expression by NPC tumor cells and the extent of T cell infiltrate still awaits further investigation." (PMID 24278236, 2013). "This suggests that CXCL9 promotes Th1/CTL-mediated anti-tumor immunity." (PMID 23408142, 2013). "Within the tumor microenvironment, cancer cells are the major source of CXCL9." (PMID 22333315, 2012). "Th17 cells may contribute to protective human tumor immunity by inducing Th1-type chemokines and stimulating CXCL9 and CXCL10 production to recruit effector cells to the tumor microenvironment." (PMID 22693525, 2012). "The majority of tumor samples (17 of 20) showed CXCL9 immunoreactivity to variable degrees." (PMID 22333315, 2012). "In addition, we analyzed CXCR3 and CXCL9 expression in neu-expressing tumors on days 3 and 5 after adoptive transfer into tumor-bearing neu-N mice." (PMID 22359647, 2012). "Tumor samples were also stained with anti-MIG/CXCL9 or anti-IP10/CXCL10 antibodies." (PMID 21067607, 2010). "CXCL9 is known to function as a potent chemoattractant for tumor infiltrating lymphocytes." (PMID 21067607, 2010). "The expression of CXCR3 receptors by CRC human tissues and by the human HT29 cells and the murine C26 tumour cells has led us to determine the ability of the corresponding ligands, CXCL9, CXCL10 and CXCL11 to affect the growth and chemotactic responses of HT29 and C26 cells in vitro." (PMID 19436305, 2009). "Given that IP-10/CXCL10 and MIG/CXCL9 are important for CCL21-DC mediated tumor regression in murine studies, we examined whether AdCCL21 transduction increased the expression of these chemoattractants in human DC." (PMID 18644162, 2008). "More recently, GPC3-CAR-T cells were engineered to co-express IL-21 and CXCL9, which, alongside blockade of the checkpoint inhibitor PD-1, were shown to offer a combo of increased cytokine secretion, proliferation, chemotaxis, and overall ameliorated anti-tumor activity." (PMID 41465318, 2025). "Notably, Vegfa macrophages and Proinflammatory macrophages exhibited downregulation of tumor angiogenesis and protumorigenic genes (e.g., Cxcl3, Cxcl1, S100a8, SPP1) and upregulation of immune cell recruitment‐associated genes (e.g., Cxcl9, Ccl5, Ccl8) in mRNA‐treated groups." (PMID 39761175, 2025).
tumor (continued). "These cells express Cxcl9, Cxcl10 and Il15, but in contrast to type 1 conventional dendritic cells, which cross-present antigens, inflammatory monocytes obtain and present peptide–major histocompatibility complex class I complexes from tumour cells through ‘cross-dressing’." (PMID 39604727, 2025). "Interferon (IFN)-induced CXCR3 ligands, CXCL9/10/11, regulate tumor angiogenesis, enhance T cell infiltration, and further position activated T cells near antigen-presenting cells within the TME, which may provide additional cues to T cells that facilitate antitumor immunity." (PMID 40230843, 2025). "Additionally, in multivariate analysis, after adjusting for baseline Ki67 levels, tumor stage, and treatment duration, CXCL9 (OR: 0.64, 95% CI: 0.41–0.89, p = 0.030) and NPY1R (OR: 1.52, 95% CI: 1.09–3.01, p = 0.047) remained significant independent predictors of Ki67 reduction." (PMID 40205245, 2025). "Next, we asked whether Cxcl9 and Il12b cDC1s segregate to different regions of the tumour." (PMID 40745918, 2025). "Low levels of these chemokines within in a tumor contributes to a “cold” tumor landscape unable to respond to immune therapies such as checkpoint inhibitors, while high CXCL9/10 contributes to “hot” tumors where effector cells are present but may not function properly." (PMID 40176808, 2025). "Therefore, the anti-tumor effects of CXCL9 + macrophages are multifaceted, encompassing both their direct killing and inhibitory effects on epithelial cells, as well as their modulation of the immune microenvironment to suppress tumor growth through other immune cells." (PMID 41325308, 2025). "Additionally, reprogramming SPP1+TAMs into CXCL9+ TAMs may offer an alternative approach to enhance anti-tumor immunity and reshape the immune landscape in HCC." (PMID 40230843, 2025). "However, data on CXCL9 role in tumor progression are contradictory." (PMID 40211394, 2025). "Unexpectedly, transient clusters of CXCL9+/PD-L1+ mDCs emerged at discrete epithelial sites weeks before any morphological signs of lesions and consistently marked regions that later developed into premalignant lesions, revealing a spatially confined, early indicator of tumor initiation." (PMID 41279770, 2025). "Moreover, IL-15 and CX3CL1 plasma levels were positively correlated with markers of inflammation and high tumor burden (fibrinogen, lactate dehydrogenase, C-reactive protein, cell-free DNA, CXCL9) at pre-lymphodepletion, a biochemical makeup that has been associated with ICANS." (PMID 38833312, 2024). "Interestingly, increased expression of CCL19, CXCL9 and CXCL10 is associated with recruitment of immature CD56bright NK cells with low perforin content in the tumor microenvironment (TME), which is thought to protect tumor cells from NK cells." (PMID 40809150, 2024). "Notably, our in vitro experiments demonstrated that although tumor cells could prime macrophages to secrete CXCL9, blockade of C5aR substantially increased CXCL9 production by THP-1 cells, suggesting the potential relevance of C5aR in human cancers." (PMID 38098230, 2024). "LIF epigenetically blocks the chemokine MIG (CXCL9), which is involved in the polarization of macrophages along the M1 pathway and ensures the recruitment of cytotoxic CD8+ T cells into the tumor, which have an antitumor effect; hence, a decrease in the level of LIF causes tumor regression." (PMID 38891915, 2024). "The EV-treated macrophages downregulated expression of M1 polarization-associated genes Cxcl9, Cxcl10 and Il12b, and had reduced capacity to attract activated T cells and to reactivate them to release IFN-γ, key components of an efficacious anti-tumor immune response." (PMID 38389103, 2024). "Therefore, this study hypothesized that the increase in CXCR3+ T cells in the blood of treatment-resistant patients might be caused by a decrease in the activation of CXCL9 and CXCL10 inside the tumor microenvironment." (PMID 39273452, 2024).